SIRT2 (sirtuin 2)
Diseases named in the same sentence as SIRT2 in open-access papers (continued):
Sharing a sentence is not in itself a finding about the gene and the disease.
ischemic stroke (19 papers, 2015 to 2024). A stroke disorder caused by obstruction of blood flow to the brain, due to thrombotic (local blood clot formation) or embolic (due to a blood clot or other material traveling from another site) event. "Our results are concordant with a recent small study of 75 ischemic stroke patients in whom higher SIRT2 in serum exosomes was associated with unfavorable 3-month functional outcome." (PMID 37794467, 2023). "SIRT2 has been found to be associated with many neurological diseases, including ischemic stroke." (PMID 35574497, 2022). "More recently, Lu and colleagues found that the Silent Information Regulator 2 (SIRT2) protein is higher in the serum EVs of ischemic stroke patients compared to non-ischemic stroke patients." (PMID 38739358, 2024). "By exploring the relationship between SIRT2 and clinical symptoms, a better understanding of the mechanism through which SIRT2 plays a role in ischemic stroke can be gained." (PMID 37684620, 2023). "In ischemic stroke mouse brains, expression of SIRT2 was upregulated and translocated into neuronal nuclei in the ischemic penumbra." (PMID 37215138, 2023). "A study of the localization and expression of SIRT1, 2, 6 and plasticity-associated proteins in the recovery period after ischemic stroke in mice showed that there was an increase in the levels of SIRT1 and SIRT2 during this recovery period." (PMID 35625059, 2022). "Treatment of mice with Activator III reduced the infarction volume, while the SIRT1 and SIRT2 inhibitor sirtinol increased ischemic damage both in the model of ischemic stroke and in the model of hemorrhagic stroke." (PMID 34680562, 2021). "It is known that Sirt2 is able to mediate myelin-dependent neuronal dysfunction at an early stage after ischemic stroke." (PMID 34680562, 2021). "The neuroprotective effects of SIRT2 inhibition have also been found in ischemic stroke, which is mediated by the downregulation of AKT/FOXO3a and mitogen-activated protein kinase (MAPK) pathways." (PMID 34108853, 2021). "In contrast, Sirt2 is usually assigned a proapoptotic role, and pharmacological inhibition or knockdown of Sirt2 can prevent neuronal apoptosis in ischemic stroke." (PMID 34360712, 2021). "A role for SIRT2 in mediating programmed necrosis, and a possible amelioration of necrotic injuries, including those that result from ischemic stroke and myocardial infarction, by inhibition of SIRT2 enzyme activity has been proposed but remains controversial." (PMID 25608039, 2015). "Pharmacological inhibition of SIRT2 blocks TNF-α-induced cell necrosis, suggesting that SIRT2 inhibitors may constitute a novel approach to prevent necrotic injury, including ischemic stroke and myocardial infarction." (PMID 39226168, 2024). "SIRT2 was proved to inhibit NLRP3 inflammasome depending on its deacetylate activity suggesting SIRT2 may influence ischemic stroke by regulating inflammasome activity." (PMID 37215138, 2023). "Moreover, the neuroprotective effect of SIRT2 inhibition on ischemic stroke is modulated via the downregulation of the protein kinase B (AKT)/FOXO3a axis and the MAPK pathways." (PMID 35813508, 2022). "It was found that the downregulation of SIRT2 protects the mouse brain against ischemic stroke." (PMID 35813508, 2022). "Interestingly, SIRT2 inhibition by AGK2 also exerted the neuroprotective effects in ischemic stroke by the downregulation of AKT/FOXO3a and MAPK pathways." (PMID 35625059, 2022). "At the early phase of ischemic stroke, SIRT2 mediates myelin-dependent neuronal dysfunction." (PMID 35528522, 2022). "SIRT2 has also been verified to regulate programmed necrosis in ischemic stroke." (PMID 34108853, 2021). "However, the neuroprotective effect of SIRT2 inhibition on ischemic stroke has also been reported, which is mediated by downregulation of AKT/FOXO3a and MAPK pathways." (PMID 34108853, 2021).
ischemic stroke (continued). "SIRT2, an NAD+-dependent deacetylase predominantly localized in the cytoplasm, was proven to play an important and paradoxical role in regulating ischemic stroke and neurodegenerative disease." (PMID 37215138, 2023). "Our work is devoted to studying the role of non-mitochondrial sirtuins SIRT1 and SIRT2 in brain cells after ischemic stroke." (PMID 35574497, 2022). "The present study characterized the SIRT2 inhibition property of the previously identified small molecule AK7 and its effects in models of three neurodegenerative conditions: PD, ALS, and ischemic stroke." (PMID 25608039, 2015). "However, AK7-mediated Sirt2 inhibition showed no therapeutic efficacy in mouse models of amyotrophic lateral sclerosis and ischemic stroke, indicating that Sirt2 inhibition only mitigates the pathophysiology of specific neurodegenerative diseases." (PMID 38474697, 2024). "Furthermore, SIRT2 inhibitors, such as AK1 or AGK2, have been reported to reduce cell apoptosis by downregulating the AKT/FOXO3a and MAPK pathways, resulting in a reduction in the ipsilateral infarct area after ischemic stroke." (PMID 37684620, 2023). "In the present review we focus on the role of non-mitochondrial SIRT1, SIRT2, and SIRT6 in the brain damage and recovery after ischemic stroke." (PMID 34680562, 2021). "Moreover, it was shown that SIRT1, SIRT2, and SIRT6 were not involved in ischemic stroke-induced penumbra cell apoptosis." (PMID 35625059, 2022).
lung carcinoma (19 papers, 2015 to 2025). "It is therefore plausible that high SIRT2 expression is an independent risk factor and is associated with a better prognosis for lung cancer patients, while a hazard ratio (HR) of less than 1 suggests a protective effect of SIRT2." (PMID 36844923, 2022). "Furthermore, we demonstrated that HRD1 deficiency decelerates lung cancer cell proliferation and tumor formation and that SIRT2 knockdown restores the cell proliferation phenotype in HRD1 knockdown cells." (PMID 31932479, 2020). "Furthermore, we found that HRD1 deficiency induces SIRT2 upregulation and inhibits the growth and tumor formation of lung cancer cells both in vitro and in vivo." (PMID 31932479, 2020). "Collectively, SIRT2 proteins secreted from macrophages were responsible for ITGB3 aK416 deacetylation of lung cancer cells." (PMID 36453571, 2023). "To explore the association of SIRT2 secretion with ITGB3‐K416 deacetylation in human cancers, we collected blood samples from lung cancer patients." (PMID 36453571, 2023). "Dramatically elevated serum SIRT2 level in lung cancer patients especially these highly metastatic SCLC patients strongly correlated with deacetylation of ITGB3 vWA domain‐K416 as well as other extracellular proteins of cancer cells." (PMID 36453571, 2023). "But macrophages pre‐treated with the SIRT2 inhibitor AGK2 effectively blocked LPS‐induced metastasis of the A549 or H1299 lung cancer cells." (PMID 36453571, 2023). "By contrast, the ligase protein HRD1 augments the growth and tumorigenicity activity of lung cancer cells by inducing sirtuin 2 ubiquitination and degradation." (PMID 37249301, 2023). "In this work, TCGA data online and independent datasets were used to determine SIRT2 expression levels and construct systematic prognostic landscapes for different types of lung cancer." (PMID 36844923, 2022). "Correlation of the mRNA expression level of SIRT2 in different stage and clinical prognostic potential in lung cancer with different clinicopathological factors." (PMID 36844923, 2022). "We examined the correlation between the expression levels of SIRT2 and the level of immune infiltration in both types of lung cancer." (PMID 36844923, 2022). "In human lung cancer A549 cells, decreased sirtuin 2(SIRT2) reduces the expression and activity of glucose-6-phosphate dehydrogenase (G6PD) by acetylation, resulting in enhanced production of ROS and IAV replication." (PMID 35967412, 2022). "Based on these data, we revealed the prognostic value of SIRT2 for several types of lung cancer, i.e., higher or lower SIRT2 expression varies in prognostic value with each type." (PMID 36844923, 2022). "Noticeably, all of the oesophageal carcinoma and lung carcinoma cell lines expressed less Sirt2 than the mean of all tested cell lines." (PMID 35008351, 2021). "Our study showed that SIRT2 expression was downregulated in lung cancer and that this change was accompanied by HRD1 upregulation." (PMID 31932479, 2020). "In lung cancer, it has been demonstrated that SIRT2 was significantly downregulated in tumor tissues as compared with paired adjacent normal tissues at the mRNA and protein levels." (PMID 33207824, 2020). "Taken together, these results suggested that HRD1 is involved in regulating lung cancer tumorigenesis and metastasis through SIRT2." (PMID 31932479, 2020). "Of note, we observed that SIRT2 expression is downregulated in human lung cancer and also negatively correlates with HRD1 expression in these cancers." (PMID 31932479, 2020). "By contrast to the tumor-suppressing role of SIRT2/4, the roles of SIRT1/6/7 and mitochondrial SIRT3/5 are strongly associated with drug resistance in lung cancer 119, 120, 124, 135, 142, 144, 146, 150-154." (PMID 31956359, 2020). "We then analyzed the levels of SIRT2 and Skp2 in 6 commonly used lung cancer cell lines, compared to NT." (PMID 26942878, 2016).
lung carcinoma (continued). "Overexpression of SIRT2 in lung cancer cell lines modulated cell proliferation, apoptosis and cell cycle, and enhanced the sensitivity to Cisplatin-induced cytotoxicity." (PMID 26942878, 2016). "We found that lung cancer cell lines contained significantly lower levels of SIRT2, compared to NT, shown by representative Western blots, and by quantification." (PMID 26942878, 2016). "To study the significance of SIRT1 and SIRT2 overexpression in human lung cancer, we analyzed their protein levels in a cohort of 105 NSCLC patients by immunohistochemistry." (PMID 25915617, 2015). "The findings of promoter methylation here may provide insight into how SIRT2 expression levels fluctuate during lung cancer progression." (PMID 36844923, 2022). "Based on these findings, SIRT2 may be involved in immune infiltration in different types of lung cancer and promote a better prognosis in LUAD instead of in LUSC." (PMID 36844923, 2022). "By investigating the association between SIRT2 expression levels and different clinical features, we expect to reveal the mechanism and relevance of SIRT2 expression levels in various cancer types, especially in patients with different clinical stages of lung cancer." (PMID 36844923, 2022). "In addition, we demonstrated that HRD1 promotes lung cancer cell metastasis and invasion by downregulating SIRT2 expression." (PMID 31932479, 2020). "Moreover, in several lung cancer cell lines, the SIRT2 levels significantly decreased and the Skp2 levels significantly increased." (PMID 26942878, 2016). "Our results support the hypothesis that SIRT1 and SIRT2 have a protumorigenic role in lung cancer, promoting cell proliferation." (PMID 25915617, 2015). "In summary, our results support the hypothesis that SIRT1 and SIRT2 have a protumorigenic role in lung cancer, promoting cell proliferation." (PMID 25915617, 2015). "Contradictory data have also been published on the role of SIRT2 in lung cancer." (PMID 25915617, 2015). "Therefore, we investigated whether the KRASMut-ERK/MAPK-c-Myc axis increases SIRT1 or SIRT2 expression in KRASMut lung cancer cells." (PMID 37779142, 2023). "Nevertheless, whether Skp2 may be deacetylated by SIRT2 in lung cancer cells is unknown." (PMID 26942878, 2016). "Thus, our data on lung cancer cell lines are consistent with those from patients' specimens, suggesting that lung cancer cells may have decreased SIRT2 and increased Skp2." (PMID 26942878, 2016). "We then incubated lung cancer cell lines SPCA1, H1299, and A549 with recombinant SIRT2 protein (rSIRT2) purified from bacteria." (PMID 36453571, 2023). "Elevated levels of SIRT2 in the serum, along with decreased ITGB3‐K416 acetylation in lung cancer patients provided new means by targeting SIRT2 in the microenvironment in order to block metastasis." (PMID 36453571, 2023). "Similar protein-protein interaction between AKR1C1 and SIRT2 was also observed from another NSCLC NCI-H1299 cells, suggesting the formation of AKR1C1-SIRT2 complex in lung cancer models." (PMID 32104503, 2020). "The enhancement of lung cancer cell proliferation and colony formation was partially abrogated by the overexpression of either HRD1 or SIRT2." (PMID 31932479, 2020). "Thus, re-expression of SIRT2 may be a promising strategy for treating lung cancer." (PMID 26942878, 2016). "Therefore, the role of SIRT1 and SIRT2 in lung cancer remains unclear." (PMID 25915617, 2015). "In order to investigate the functional role of SIRT1 and SIRT2 in NSCLC, we downregulated their expression in two lung cancer cell lines, A549 and H1299, using two different siRNAs for each gene." (PMID 25915617, 2015). "Changes in proliferation were assessed after SIRT1 and SIRT2 downregulation in lung cancer cell lines using siRNA-mediated technology or tenovin-1, a SIRT1 and SIRT2 inhibitor." (PMID 25915617, 2015).
lung carcinoma (continued). "Notably, silent information regulator 2 (SIRT2) is secreted by macrophages upon TLR2 or TLR4 activation, further promoting the metastatic process of lung cancer." (PMID 40166469, 2025). "Therefore, a close connection between SIRT2 secretion from macrophages and ITGB3 vWA domain (K416) deacetylation in the tumor microenvironment of human lung cancer patients has been established." (PMID 36453571, 2023). "Upregulation of HRD1 in lung cancer patients leads to decreased SIRT2 expression and enhanced cell proliferation and tumorigenesis, and HRD1 and SIRT2 expression levels may serve as prognostic markers for lung cancer." (PMID 31932479, 2020). "On the basis of these results, we propose a mechanism of lung tumorigenesis that involves HRD1-mediated downregulation of SIRT2 and suggest that interventions targeting HRD1 activity could be a potential therapeutic strategy to treat patients with lung cancer." (PMID 31932479, 2020). "To investigate whether SIRT2 could have a similar expression pattern in lung cancer cells, we examined the expression levels of HRD1 and SIRT2 in lung cancer tissues (n = 8) and matched adjacent normal lung tissues (n = 8) using Western blotting." (PMID 31932479, 2020). "SIRT2 and HRD1 expressions are inversely correlated in lung cancer samples." (PMID 31932479, 2020). "Notably, immunofluorescent staining detected SIRT2 proteins either barely overlay with ITGB3‐aK416 positive lung cancer cells or sporadically overlay with CD68 positive macrophages, indicating SIRT2 proteins visualized here were mainly distributed in the extracellular space." (PMID 36453571, 2023). "Although both SIRT2 and HDAC6 bound the KRASMut protein, neither greatly affected the acetylation or activity of the KRASMut protein in lung cancer cells." (PMID 37779142, 2023). "In lung cancer, previously published results about the role of SIRT1 and or SIRT2 have not provided a clear and definite answer." (PMID 25915617, 2015).
melanoma (19 papers, 2017 to 2026). A malignant, usually aggressive tumor composed of atypical, neoplastic melanocytes. "Low SIRT2 levels alter the expression of tyrosine kinase receptors and induce melanoma cell susceptibility to the multikinase inhibitor dasatinib." (PMID 31091806, 2019). "We also showed that SIRT2 loss substantially decreased the migration of melanoma cells, and treatment with dasatinib further increased this inhibition of migration." (PMID 31091806, 2019). "Transcriptome analysis demonstrated that SIRT2 has important regulatory roles in the expression of multiple genes associated with the molecular signatures of melanoma progression." (PMID 31091806, 2019). "Here, using several methods, we demonstrate that melanoma cells with knockdown of sirtuin 2 (SIRT2) are more susceptible to cisplatin, suggesting that this sirtuin might be involved in the mechanisms of melanoma resistance to this drug." (PMID 34068624, 2021). "Similarly, genes related to melanoma invasion were downregulated in SIRT2-deficient melanoma cell lines (e.g., HLA-DRA, IL-6, CD74, and HLA-DRB1 in the SSW30 clone, Dataset S1; PTPRZ1, FST, and NRCAM in the SSM15 clone, Dataset S2)." (PMID 31091806, 2019). "This hypothesis is also consistent with the observations that dasatinib mediates different protein phosphorylation profiles in SIRT2-deficient melanoma cells than in control cells." (PMID 31091806, 2019). "Systemic overexpression of SIRT2 accelerates melanoma growth and reduces NK cell infiltration, as well as impairing NK cell cytotoxicity." (PMID 41425553, 2025). "The direction of association of SIRT2 expression changes in NCI-TPW contrasts with earlier reports of increased sensitivity to dasatinib in melanoma cell lines with SIRT2 knockdown." (PMID 38369747, 2024). "Systemic overexpression of SIRT2 promotes melanoma progression in immune-competent mice by suppressing the infiltration and function of NK cells in TME." (PMID 35693795, 2022). "SIRT2 is overexpressed in melanoma, and inhibition of SIRT2 reduces melanoma cell growth and clone formation." (PMID 35493297, 2022). "B16-F10 cells with vector control (Vehicle), Sirt2 knockout (Sirt2-KO), and Sirt2 overexpression (Sirt2-OE) were inoculated subcutaneously into wild-type mice using the subcutaneous melanoma model." (PMID 34155309, 2021). "In summary, this work suggests a novel relationship between systemic SIRT2 expression, NK cell behavior in the tumor microenvironment, and melanoma tumor progression." (PMID 34155309, 2021). "The results of the neutral red viability assay showed increased cisplatin cytotoxicity in melanoma cells with downregulated SIRT2 expression." (PMID 34068624, 2021). "Using genetic murine models, we demonstrate that systemic overexpression of SIRT2 promotes melanoma tumor progression through suppression of NK cell tumor infiltration and activity." (PMID 34155309, 2021). "In this study, we examined SIRT2’s effect on allograft melanoma tumor progression using SIRT2 transgenic and wild-type mouse models, as well as underlying changes in NK cell function within the TME." (PMID 34155309, 2021). "Recently, SIRT2 was identified as important regulator of melanoma cells functions, such as cell motility, proliferation, and particularly resistance to dasatinib in melanoma." (PMID 33918490, 2021). "As in the melanoma model, Sirt2-KI mice exhibited faster tumor progression in terms of tumor volume (P = 0.0045, 0.0055, 0.0013, and 0.0001) and final weight (P = 0.0003)." (PMID 34155309, 2021). "Using murine allograft melanoma models, our results suggest increased systemic expression of SIRT2 promotes tumor progression." (PMID 34155309, 2021). "Contrarily, SIRT2 loss has also been shown to confer resistance to BRAF and MEK inhibitors in BRAF mutant melanoma." (PMID 33178616, 2020). "Previously, SIRT2 was reported to increase the resistance of anticancer drugs in melanoma and nasopharyngeal carcinoma." (PMID 33207824, 2020).